AR (androgen receptor)
Diseases named in the same sentence as AR in open-access papers (continued):
Sharing a sentence is not in itself a finding about the gene and the disease.
prostate carcinoma (continued). "Experimentally, exogenous expression of HNF4G in prostate cancer cells leads to expression of the GI transcriptome and resistance to AR pathway inhibition." (PMID 40553565, 2025). "The regulation of MPC expression by the androgen receptor (AR) is a crucial control element in the metabolism of androgen receptor-positive and castration-resistant prostate cancer cells, which enables the growth of these tumor cells." (PMID 40489535, 2025). "For example, a recent study identified CDK12 to be critical for prostate cancer cell survival and its inhibition suppressed AR signalling." (PMID 40163908, 2025). "Using CRISPR knockout and small interfering RNA techniques, we confirmed that growth of AR-positive prostate cancer cells was significantly suppressed by targeting p300/CBP." (PMID 41044247, 2025). "This study demonstrates that androgen deprivation therapy (ADT) significantly reduces TMPRSS2 expression in the lung tissue of prostate cancer patients, with direct AR antagonists exerting the most pronounced effect." (PMID 41150771, 2025). "Similar to AR, which is well-established to be essential for cell cycle regulation in prostate cancer cells, AR-V7 promotes castration- and ARPI-resistance by driving cell cycle progression." (PMID 41237749, 2025). "Our observations are in keeping with results from prior studies showing the role of AR in modulating DNA repair pathways in prostate cancer, thus extending its relevance to ER+ve breast cancer." (PMID 40940753, 2025). "Treatment with Protac-A in androgen-dependent prostate cancer cells results in G1 phase blockade, mediated by the degradation of the AR-specific inhibitor of hormones." (PMID 40771930, 2025). "The pursuit of understanding castration resistance in prostate cancer has long been dominated by investigations into tumor‐intrinsic mechanisms, particularly those involving androgen receptor (AR) signaling dysregulation." (PMID 40917018, 2025). "A 1 h pre-treatment with CBPD-409 completely attenuated ligand-induced transcriptional activity of AR in prostate cancer cells." (PMID 41044247, 2025). "A recent report showed that the DHT treatment of prostate cancer cells induced the formation of nuclear AR/Sp1 and AR/Sp3 complexes on the GPER1 gene promoter to decrease transactivation." (PMID 39858066, 2025). "OC’s ability to inhibit SMYD2 has significant implications for prostate cancer treatment, particularly in disrupting the methylation of the androgen receptor (AR) at lysine residues 6–42." (PMID 40564985, 2025). "The AR is a nuclear hormone receptor that plays a pivotal role in the development and progression of prostate cancer." (PMID 41235005, 2025). "Together, PSMA, PCA3, and AR, which play pivotal roles in prostate cancer development, represent key aspects of tumor biology, such as cancer progression and androgen-dependent growth." (PMID 39859417, 2025). "FOXA1 is crucial for regulating the expression of numerous genes, particularly AR, during prostate cancer development and progression." (PMID 40356745, 2025). "In prostate cancer, THZ1 caused tumour regression of AR-driven CRPC mouse xenograft models by suppressing AR-dependent oncogenic transcription programs." (PMID 40163908, 2025). "The RNA and protein level of KDM5B was elevated in localized and advanced prostate carcinomas, and it was shown that KDM5B together with LSD1 was implicated in the regulation of expression of AR target genes." (PMID 40940894, 2025). "Androgen receptor (AR) alterations contribute to treatment resistance against androgen receptor signaling inhibitors in metastatic castration‐resistant prostate cancer." (PMID 40558023, 2025).
prostate carcinoma (continued). "Although previously reported as a tumor suppressor in glioblastoma, DHX15 has also been shown to promote prostate cancer by enhancing androgen receptor transcriptional activity, and its depletion has been linked to leukemia pathogenesis." (PMID 40561176, 2025). "In prostate cancer, GABARAPL1 is regulated by the androgen receptor (AR), which affects the proliferation of prostate cancer cells." (PMID 40900801, 2025). "AR signalling plays key roles in regular prostate development and, in prostate cancer, is upregulated." (PMID 40699691, 2025). "Prostate cancer (PCa) remains a major therapeutic challenge due to aberrant androgen receptor signaling and a remodeled tumor microenvironment." (PMID 41330917, 2025). "Advanced prostate cancer is treated with androgen receptor (AR) signaling inhibitors, which are initially effective, but most patients eventually develop resistance and progress to castrate-resistant prostate cancer (CRPC)." (PMID 41061530, 2025). "This subtype of prostate cancer is characterized by tumor cells that often grow independently from the androgen receptor signal transduction pathway, losing its typical features of prostate adenocarcinoma." (PMID 40342821, 2025). "Apalutamide, an androgen receptor inhibitor, has shown good efficacy in treating prostate cancer (PCa)." (PMID 40051628, 2025). "Organic extracts of some C. comatus were screened to test their antiandrogenic activity and their capacity to interfere with the androgen receptor, which is the major drug target of prostate cancer therapy." (PMID 39852473, 2025). "The development of innovative therapeutic approaches that suppress AR signaling through novel mechanisms of action remains an urgent unmet clinical need for prostate cancer medicine." (PMID 39787247, 2025). "For example, small molecules targeting NONO have been shown to induce its assembly into nuclear puncta, effectively reducing androgen receptor expression in prostate cancer cells." (PMID 40691806, 2025). "On the other hand, in advanced prostate cancer, the androgen receptor blockade enhances PPARG lipogenic signaling and the acquisition of a prostate NE phenotype, revealing mutual interrelationships." (PMID 40869121, 2025). "AR can affects the development of prostate cancer by regulating transcriptional networks, genome stability, and DNA repair, as evidenced by the emergence of gene fusion." (PMID 41200193, 2025). "ARCC-4 induces VHL-mediated degradation of AR with a DC50 value of 5 nM in prostate cancer cell lines, effectively reducing AR protein levels." (PMID 40507351, 2025). "While AR directly regulates B7-H3 in prostate cancer, its role in melanoma is less defined; nonetheless, B7-H3 is highly expressed and contributes to immune evasion." (PMID 40940929, 2025). "A study on prostate cancer demonstrated that betulin significantly downregulated SREBP2 and its target genes, exhibiting inhibitory effects on the downstream activity of the androgen receptor (AR), which suppressed prostate cancer progression." (PMID 40308757, 2025). "AR, a nuclear receptor family member, is persistently activated in malignancies such as prostate cancer." (PMID 41049269, 2025). "A recent article reported that USP11 can deubiquitinate and stabilize the MYC and AR proteins, thereby promoting prostate cancer progression." (PMID 39990228, 2025). "Lastly, VCaP-CR cells exhibit the TMPRSS–ERG fusion which is found in over half of patients with prostate cancer, as well as AR-FL amplification through AR copy-number gain." (PMID 40704654, 2025). "Currently, androgen deprivation therapy (ADT), along with newer second-generation androgen receptor (AR) antagonists are the standard of care for patients with advanced or recurrent prostate cancer." (PMID 40282446, 2025). "•The androgen receptor (AR), a transcription factor that is the primary therapeutic target in advanced prostate cancer, is a key driver of dysregulated transcription in prostate cancer." (PMID 40163908, 2025).
prostate carcinoma (continued). "Depletion of either FKBP5 or FKBP4 in prostate cancer cells reduces AR dimer formation, chromatin binding, and phosphorylation, suggesting defective AR signalling." (PMID 41249932, 2025). "Further research is needed to determine the exact role of circPCDH11Y in AR signaling during prostate cancer transdifferentiation." (PMID 40008007, 2025). "The AR, known as a primary mediator in prostate cancer and male reproductive tissue maintenance, functions by binding to androgens, male sex hormones, and subsequently acting as a transcription factor to regulate gene expression." (PMID 39980567, 2025). "Herein, we demonstrate that NXP800, a heat shock factor 1 pathway inhibitor in clinical development, activates the unfolded protein response and inhibits AR- and E2F-mediated transcription as well as the growth of treatment-resistant prostate cancer models." (PMID 39787247, 2025). "We encapsulated siRNA against the androgen receptor (AR), a key driver in prostate cancer, with the ultimate goal to include AR knockdown as a measure for functional transfection and tumor treatment." (PMID 40115963, 2025). "In short, elucidating t-CDK function in the TME, including its interplay with AR, will be critical to advance the field's understanding of prostate cancer pathobiology as well as the development of t-CDK-based therapeutic approaches." (PMID 40163908, 2025). "Studies have shown that in the presence of high levels of androgens, AR activity can enhance the Rb1 tumor-suppressor function and downregulate c-myc tumors, leading to suppressed growth in prostate cancer cell lines." (PMID 40075623, 2025). "Combined therapy of AR antagonists with ferroptosis inducers markedly reduced the growth of AR-positive prostate cancer, even in tumors resistant to hormonal therapy." (PMID 39935430, 2025). "ACSL4 promotes the malignant progression by upregulating the overall protein myristoylation in estrogen receptor (AR)-dependent prostate cancer cells." (PMID 40050614, 2025). "The clinical concern lies in how to detect resistance to AR antagonists earlier and provide effective treatment options for advanced prostate cancer." (PMID 39931089, 2025). "In prostate cancer, TOPK promotes the expression of the androgen receptor splice variant (ARv7), driving androgen-independent growth and regulating tumor-specific radio-sensitivity." (PMID 40826334, 2025). "Considering those pathways beyond the UPR, RNA-seq analyses demonstrated that treatment with NXP800 impacted other key pathways, including AR, MYC, and E2F activity, implicated in prostate cancer treatment resistance." (PMID 39787247, 2025). "It is a highly potent PROTAC that induces rapid and near-complete degradation of the androgen receptor in prostate cancer models." (PMID 40574056, 2025). "In line with this, AA induces AR-dependently the genetic program of cellular senescence in both prostate cancer types." (PMID 40072554, 2025). "A recent study summarized the roles and mechanisms by which transcription factors assist AR in promoting prostate cancer progression, proposing a therapeutic strategy aimed at targeting and silencing specific nodes within the transcriptional network." (PMID 39963114, 2025). "The GABA shunt has been shown to be important for castration-resistant prostate cancer cells as GABA promotes the nuclear localization of the androgen receptor." (PMID 39923095, 2025). "Despite the importance of the AR‐NTD as a drug target for novel treatments against advanced prostate cancer, little is known about its range of conformations, and how these are affected by the binding of small drug‐like molecules." (PMID 39665260, 2025). "Lineage enrichment analysis revealed that enhancer-driven AR-positive prostate cancer, neuroblastoma, rhabdoid tumor and acute myeloid leukemia were among the most sensitive to CBPD-409 treatment." (PMID 41044247, 2025).
prostate carcinoma (continued). "Prostate cancer cells can evade AR blockade-mediated cell death during treatment via elevated GR signaling, responsible for MAO-A upregulation in epithelial and stromal cells." (PMID 39714760, 2025). "Bioinformatic analysis of patient‐derived xenografts (PDXs), cell lines, and organoids identified three intrinsic transcriptional subtypes of mCRPC, including AR‐pathway prostate cancer (ARPC), MSPC, and neuroendocrine prostate cancer (NEPC) cells." (PMID 39651632, 2025). "ER and AR are highly expressed in most types of breast and prostate cancer, driving cancer cell growth in response to hormones." (PMID 40032852, 2025). "OTUD6A promotes the proliferation of prostate cancer cells by deubiquitinating and stabilizing the Brg1 and AR proteins." (PMID 41050073, 2025). "Direct co-culture of AR-dependent and -independent prostate cancer cell lines (LNCaP, C4-2B, and PC3) induced molecular and functional changes similar to those observed in vivo." (PMID 40596459, 2025). "Treatment with LHR-siRNA can prevent LH-mediated proliferation and androgen synthesis of prostate cancer cells, and downregulate the expressions of AR, PSA, PKA, ERK1/2, PI3K, AKT2 and HER2." (PMID 41347146, 2025). "Finally, studying mutation cooperativity reveals how interactions between multiple gene mutations might also contribute to drug resistance, assisting in identifying new resistance mechanisms and addressing the challenges posed by AR mutations in prostate cancer treatment comprehensively." (PMID 40008000, 2025). "To confirm our findings in patients with prostate cancer, we leveraged AR cistrome data from patient tissues to distinguish CRPC-specific AR neo-enhancers from normal AR enhancers." (PMID 41044247, 2025). "For example, the androgen receptor (AR) forms liquid-like condensates in prostate cancer cells upon androgen stimulation, which correlates with transcriptional activity and oncogenic programs." (PMID 40231263, 2025). "Here, we present the case of a 90-year-old man with metastatic castrate resistant prostate cancer (mCRPC) and primary resistance to androgen deprivation, second-generation androgen receptor inhibitors, and docetaxel chemotherapy." (PMID 41589251, 2025). "The small molecule atraric acid (AA) has an ester group and had been identified as the first natural androgen receptor antagonist that inhibits prostate cancer cell growth and induces cellular senescence in cancer cells." (PMID 40072554, 2025). "In prostate cancer, AR signaling drives the metabolic reprogramming of tumor cells by enhancing the expression of genes involved in glycolysis, lipid synthesis and mitochondrial function." (PMID 40563466, 2025). "Cytotoxicity profiling across >900 cell lines revealed that tumors with high H2BNTac, including AR-positive prostate cancer, are selectively dependent on p300/CBP." (PMID 41044247, 2025). "The androgen receptor signaling inhibitor enzalutamide (Enz) is one the primary therapeutic drugs for advanced prostate cancer (PCa)." (PMID 40849495, 2025). "Targeting this pathway has emerged as a promising strategy to overcome resistance, with preclinical studies showing that inhibitors of STAT3/JAK2, such as AG490, can reduce STAT3-mediated AR activation and hinder prostate cancer cell growth." (PMID 41235005, 2025). "It has been suggested that AR engages the cell cycle engine, facilitating the proliferation and survival of prostate cancer cells." (PMID 40001891, 2025). "Copper metabolism intersects with androgen receptor (AR) signaling to drive prostate cancer progression." (PMID 40660923, 2025). "Variations in RNF20 expression and its interaction with AR play a complex role in prostate cancer progression, offering potential targets for therapeutic intervention." (PMID 40356745, 2025). "Since NF-κB plays a key role in resistance to castration or androgen receptor (AR) antagonists, its inhibition represents a relevant therapeutic approach in advanced prostate cancer." (PMID 40126263, 2025).
prostate carcinoma (continued). "Hormonotherapy suppresses the AR signalling essential for survival of prostate cancer cells and acts on both local and systemic disease, while MDT eradicates known metastatic sites but does not address micrometastatic diseases." (PMID 40282432, 2025). "EZH2 also contributes to prostate cancer development by directly interacting with AR, enhancing AR activity, and modulating the transcription of its downstream target genes." (PMID 40959108, 2025). "Although these mechanisms are best defined in prostate cancer, in vivo melanoma models confirm that high AR activity enhances metastatic spread." (PMID 40940929, 2025). "LKB1 inactivation led to AR-independent lineage plasticity and global DNA hypomethylation during prostate cancer progression." (PMID 39743630, 2025). "This has potential clinical relevance in large patient groups that are already treated with androgen/AR-modulating drugs (e.g., for prostate cancer, prostate hyperplasia, hypogonadism or gender dysphoria)." (PMID 39910039, 2025). "In its initial stages, prostate cancer is highly reliant on androgen receptor signaling for cell growth and proliferation, and the mainstay of treatment of advanced disease is androgen deprivation therapy (ADT)." (PMID 40002188, 2025). "Prior in vitro and in vivo studies in mouse models of hepatocellular carcinoma and prostate cancer have demonstrated that AR overexpression negatively attenuates anti-PD-L1, and that AR and PD-L1 dual blockade enhances the overall survival and T cell function." (PMID 41305010, 2025). "MET is a potent oncogene down‐regulated by AR in prostate cancer, which explains its prevalence in advanced stages and bone metastases." (PMID 39374163, 2025). "There is also evidence of increased overall survival of patients with prostate cancer on docetaxel when paired with an AR inhibitor such as abiraterone." (PMID 41038711, 2025). "This supports further investigation of targeting cellular response to heat stress components as a therapeutic strategy to overcome persistent AR signaling in lethal prostate cancer." (PMID 39787247, 2025). "In prostate cancer, hyperactivation of androgen receptor (AR) signaling promotes tumorigenesis and castration-resistant disease, partly by enhancing DNA repair capacity." (PMID 40940753, 2025). "Enzalumide is a new generation of AR antagonist, and its drug resistance leads to prostate cancer becoming a more refractory tumor." (PMID 41347146, 2025). "The AR is a targetable molecule widely used in the treatment of prostate cancer; however, its role in gliomas is still not well understood." (PMID 41153666, 2025). "Dysregulated androgen receptor (AR) signaling has been identified as a key driver in prostate cancer development, which has led to the use of androgen deprivation therapy (ADT) as the mainstay treatment for advanced or metastatic disease." (PMID 41200281, 2025). "Altogether, these data indicate that NKX3.1 is necessary and sufficient for prostate cancer growth, and like AR, functions as an oncogene in a context-dependent manner." (PMID 39858088, 2025). "The AR signaling pathway is integral to normal prostate development and function, and its aberrant activation drives the initiation and progression of prostate cancer." (PMID 40432836, 2025). "Androgen‐deprivation therapy (ADT), employing medications such as abiraterone and enzalutamide, serves as an AR‐targeted approach to impede the advancement of prostate cancer." (PMID 39948708, 2025). "Androgen receptor (AR) PET imaging has recently emerged as a valuable tool in prostate cancer research and management." (PMID 40265741, 2025). "Apalutamide, like bicalutamide, is an androgen receptor (AR) antagonist, but it has a stronger binding affinity for AR, inhibiting its activity and suppressing the growth and spread of prostate cancer cells." (PMID 41158860, 2025). "The growth and proliferation of almost all prostate cancer (PCa) is driven by the androgen receptor (AR)." (PMID 40833121, 2025).